INS (insulin)
Diseases named in the same sentence as INS in open-access papers (continued):
Sharing a sentence is not in itself a finding about the gene and the disease.
type 1 diabetes (continued). "Whatever age it presents, type 1 diabetes is associated with rapid requirement for insulin and risk of ketoacidosis, suggesting that it is not a milder phenotype if diagnosed later in life." (PMID 29199115, 2018). "The importance of this finding for development of type 1 diabetes remains to be determined, but in general lower blood perfusion in islets could compromise beta cell function through hypoxia or limited dispersal of insulin into the systemic circulation." (PMID 29209740, 2018). "It has been previously shown that type I diabetes could be cured by transplantation of insulin-producing islet cells from a donor pancreas." (PMID 29770323, 2018). "However, the urgent need for a new option to treat type 1 diabetes is necessary due to the adverse effects accompanied by insulin treatment and the difficulties in maintaining metabolic balance." (PMID 30013600, 2018). "Type-1 diabetes is a condition caused by the lack of insulin hormone, which leads to an excessive increase in blood glucose level." (PMID 30693047, 2018). "There is clearly an urgent public health need for such innovation: the standard approach to self-management of Type 1 diabetes requires a subtle and sophisticated balancing act of carbohydrate intake, physical activity, and insulin dosing to maintain blood glucose homeostasis." (PMID 30234092, 2018). "However, we expect the proportion of type 1 diabetes and its impact was negligible because the incidence of PaC in insulin users was very small." (PMID 29946194, 2018). "Findings of the present review suggest that low-carbohydrate intakes may assist in reducing or preventing hyperinsulinemia in type 1 diabetes by decreasing the absolute amount of insulin required for tight glycaemic control." (PMID 29596460, 2018). "miR-146a-5p has been reported to be dysregulated in type I diabetes mellitus patients and may be involved in the pathways related to immune function, cell survival, proliferation, and insulin biosynthesis and secretion." (PMID 29963250, 2018). "In this paper, we explore the accuracy of HR and EE estimates from 2 popular activity monitors to determine if the accuracy of these wearables is sufficient for use within medical applications such as automated insulin delivery systems for use within type 1 diabetes glucose management." (PMID 30530451, 2018). "As mentioned, the standard treatment of insulin-dependent diabetes is insulin therapy." (PMID 29373983, 2018). "We find that individuals with type 1 diabetes possessing lower innate inflammatory bias at the time of clinical onset, as measured through plasma-induced transcription, are more likely to have slower rates of decline in residual insulin secretion." (PMID 30167736, 2018). "This is reflected by the high number of individuals hospitalized for whom the main diagnosis reported as DM was “unspecified DM—E14” (n = 68,987), and “insulin-dependent hospitalizations—E10” (n = 38,883), significantly higher than those reported as “non-insulin dependent diabetes—E11”." (PMID 29419786, 2018). "Diabetes type 1 occurs when the immune system targets the insulin producing cells in the pancreas." (PMID 29334951, 2018). "The condition for type 1 diabetes includes impaired beta pancreatic cell leading to failure of insulin secretion production, and the condition of the patient can be treated by means of injection of insulin." (PMID 30046337, 2018). "Dispensing of insulin registered in the Norwegian Prescription Database is likely to detect nearly all cases of type 1 diabetes, and our algorithm for diagnosis of type 1 diabetes combining registers is likely to ensure true type 1 diabetes in the vast majority of cases." (PMID 29934759, 2018). "Intensive insulin therapy improves outcomes of patients with type 1 diabetes (T1D)." (PMID 29649221, 2018).
type 1 diabetes (continued). "This points not only to beta cell loss as a cause of type 1 diabetes, but also suggests an insulin-secretory dysfunction among the residual, non-inflamed islets in some individuals." (PMID 30255378, 2018). "We notice a finer granulation in the islets of individuals with type 1 diabetes; whether this might, in part, influence the reduced sulfatide-staining that is seen in insulin granules, is unknown." (PMID 29671030, 2018). "PTPN2 has been implicated in the regulation of insulin signaling and glucose homeostasis and is also associated with chronic inflammatory and autoimmune diseases such as rheumatoid arthritis (RA), Crohn's disease, periodontitis, and type 1 diabetes mellitus (T1DM)." (PMID 30246029, 2018). "To date, trials of hESC-derived products are underway in several conditions, including macular degeneration, type I diabetes mellitus (for re-establishing insulin-secreting beta cells), spinal cord injury, and heart failure, with the limited results published so far demonstrating their safety." (PMID 29703701, 2018). "Persons with type 1 diabetes require insulin for survival; insulin may be given as a daily shot or continuously with an insulin pump." (PMID 29596402, 2018). "Although lipohypertrophy is not believed to be caused by immunological factors, insulin antibody titres have been reported to correlate with the degree of lipoatrophy and lipohypertrophy in young people with type 1 diabetes." (PMID 30116732, 2018). "In addition, increases in CRP, but not in CAMs, have been shown to depend on the degree of weight gain in insulin-treated patients with type 1 diabetes." (PMID 29101422, 2018). "Monitoring of patient physical activity levels may be helpful in implementing insulin and/or nutritional strategies to optimize glucose control in type 1 diabetes." (PMID 30530451, 2018). "The main cause of type 1 diabetes is the lack of insulin action resulting from the destruction and loss of β pancreatic islet cells, which promote the synthesis and secretion of insulin." (PMID 30123316, 2018). "These conclusions are supported by in vitro studies showing that the immediate post-isolation deficit in glucose-induced insulin secretion in the islets of people with type 1 diabetes may improve with time in culture." (PMID 30255378, 2018). "However, only a few studies are available reporting the impact of life style on required medication other than insulin and metabolic parameters in type 1 diabetes patients." (PMID 29529063, 2018). "However, this and our earlier reports show significantly lower HbA1c and insulin requirements in remitters during the early phase of type 1 diabetes." (PMID 29768449, 2018). "For example, the hypothesis and results of the present study are in line with the recent finding that insulin often acts as an autoantigen in type 1 diabetes." (PMID 29568705, 2018). "In a study comparing continuous subcutaneous insulin infusion (CSII) and multiple injections of insulin in type 1 diabetes, although glycemic control was similar among the two treatment groups after 24 months, improvements were observed in CNFL, CNFD, and CNBD only in the CSII group." (PMID 30035129, 2018). "At admission, most type 1 diabetes patients used some kind of intensified insulin therapy (N = 84, 77%), while only 10% employed Functional (basis/bolus) insulin therapy (FIT), 12% used Conventional insulin therapy (CIT), and only one chose basal insulin alone." (PMID 29529063, 2018). "Case patient #1 was a 20-year-old female with type 1 diabetes on a basal-bolus insulin regimen." (PMID 30369948, 2018). "There is reasonable evidence from both RCTs and observational studies that structured education (defined as insulin self-management and/or specific training in hypoglycaemia avoidance) leads to reductions in the rates of severe hypoglycaemia in type 1 diabetes, while improving glycaemic control." (PMID 28660491, 2018).
type 1 diabetes (continued). "We found that three consecutive doses of 50 or 75 mg/kg STZ administered to high fat-fed mice induced a phenotype that was more akin to type 1 diabetes, where pancreatic insulin content was markedly diminished and thus glucose-mediated insulin secretion was almost absent." (PMID 29854823, 2018). "Optimized insulin therapies, increased use of continuous glucose monitoring/insulin pumps and most importantly the arrival of reliable closed loop systems will undeniably lead to a reduction in the burden of complications that arise from type 1 diabetes." (PMID 30356664, 2018). "Thus, we have shown that furanocembranolides induce beta-cell proliferation and protection, maintaining functional beta-cell mass and insulin production in type 1 diabetes." (PMID 28914811, 2017). "Type 1 diabetes (T1D) is an autoimmune disease characterized by progressive infiltration of pancreatic islets of Langerhans by immune cells and subsequent destruction of insulin-producing beta cells." (PMID 29403481, 2017). "People with type 1 diabetes need to inject insulin in order to survive." (PMID 28620331, 2017). "Amongst patients on insulin without oral antiglycaemic medications, it could be hypothesized that patients taking insulin alone were more likely to have Type-I diabetes with a longer disease duration affecting renal-vasculature." (PMID 28460637, 2017). "On the other hand, a direct role of insulin was inconsistent with the absence of any increase in cancer risk in Type 1 diabetes patients, who experienced a much longer use of insulin in their life." (PMID 29070034, 2017). "This study aims to evaluate whether the protective effects of atorvastatin and insulin on renal function and renal organic anion transporter 3 (Oat3) function involve the modulation of oxidative stress and pancreatic function in type 1 diabetic rats." (PMID 29051569, 2017). "In conclusion, MBL levels are significantly reduced following the initiation of insulin pump therapy in type 1 diabetic patients, despite a significant reduction in total insulin dose, but the change was not correlated with indicators of improved glycaemic control." (PMID 29318157, 2017). "In type 1 diabetes, pancreatic cells produce insulin (beta cells)." (PMID 28957355, 2017). "Therefore, to advocate for NCD care and research in humanitarian settings, a disease, like diabetes type 1 and the need to ensure insulin supply, can be chosen as “the show case”, with which to build a case." (PMID 28932259, 2017). "Currently, whole pancreas or islet transplantation is the only cure for people with type 1 diabetes (T1D) and, due to the autoimmune nature of the disease, MSCs have been utilised either natively or transdifferentiated into insulin-producing cells (IPCs) as an alternative treatment." (PMID 28279194, 2017). "Furthermore, the influence of insulin on the daily expression of hepatic CBRs is analyzed in streptozotocin (STZ)-induced type 1 diabetes rats." (PMID 28837063, 2017). "Indeed, there are reports that islet transplantation can successfully restore long-term endogenous insulin production and glycemic stability in subjects with type I diabetes mellitus and some severe cases of pancreas fibrosis." (PMID 28594910, 2017). "It remains to be seen whether recent advances in continuous glucose monitoring and closed-loop insulin delivery will be effective for improving late gestation glucose control and reducing perinatal morbidity in type 1 diabetes pregnancy." (PMID 28597075, 2017). "Intensive insulin therapy is the standard of care in the management of type 1 diabetes." (PMID 28094136, 2017). "CGM should be offered to all pregnant women with type 1 diabetes using intensive insulin therapy." (PMID 28923465, 2017). "These factors may contribute to the notable variability in insulin requirements, which makes self-management of type 1 diabetes challenging." (PMID 28114938, 2017).
type 1 diabetes (continued). "The objective of this study is to determine the effectiveness of a 3-month day-and-night home closed-loop glucose control combined with a pump suspend feature, compared with sensor-augmented insulin pump therapy in youths and adults with suboptimally controlled type 1 diabetes." (PMID 28710224, 2017). "Although the treatment of diabetes type 1 with insulin was quite successful in the past using pig insulin and only recently recombinant human insulin, complications were often observed, mainly due to insufficient compliance of the patients leading to limb amputation and blindness." (PMID 28874166, 2017). "The ADA followed, stating that ‘adding metformin to insulin therapy may reduce insulin requirements and improve metabolic control in overweight/obese patients with poorly controlled type 1 diabetes’." (PMID 28770327, 2017). "Factors that increase the body’s requirement for insulin, such as high levels of sugar, may hasten the progression to clinical onset of type 1 diabetes in persons with beta cell autoimmunity." (PMID 28550517, 2017). "Biotin-mediated induction of glucokinase might be of particular benefit in type 1 diabetics, in whom hepatic insulin exposure and glucokinase expression is constantly subnormal despite subcutaneous insulin therapy." (PMID 28335416, 2017). "Type 1 diabetes mainly develops during childhood and requires exogenous administration of insulin." (PMID 28957355, 2017). "Later that year, the UK National Institute for Health and Care Excellence (NICE) replicated our meta-analysis and went on to recommend metformin for adults with type 1 diabetes and a BMI ≥25 kg/m2 who ‘want to improve glucose control while minimising their effective insulin dose’." (PMID 28770327, 2017). "Importantly, 1.6% of thestudy participants with insulin-dependent diabetes stored their insulin outside arefrigerator." (PMID 28780910, 2017). "Already in stage 1 of type 1 diabetes, fluctuations of insulin secretion may be detected, probably due to reversible beta cell stressors rather than beta cell death per se." (PMID 28550517, 2017). "Type I diabetes (insulin dependent diabetes) is an autoimmune disease that causes the beta cells of the pancreas to secrete little or no insulin." (PMID 28445415, 2017). "Metformin is quite frequently used off-label in type 1 diabetes to limit insulin dose requirement." (PMID 28770327, 2017). "In summary, this study demonstrated that UCPCR provides a robust and practical means for assessing insulin secretion during pregnancy, and provides a practical methodology to assess in future studies the potential for β-cell adaptation in women with type 1 diabetes." (PMID 28090333, 2017). "Since the use of atorvastatin and insulin showed great potential benefits in the preservation of renal and pancreatic function in rats with diabetes type 1, further study is recommended to investigate whether these benefits could also be conferred in humans." (PMID 29051569, 2017). "Patients should be treated using general insulin dosing and regimen guidelines for type 1 diabetes." (PMID 28101143, 2017). "Therefore, FT1D are similar as acute-onset diabetes and typical type 1 diabetes in insulin treatment and prognosis in children." (PMID 29082260, 2017). "In addition, in patients with type I diabetes need to receive exogenous insulin, it also be difficult to estimate own insulin secretion by measuring insulin in serum." (PMID 29296240, 2017). "Insulin and insulin analogues are the main therapeutical agents for type 1 diabetes." (PMID 29285313, 2017). "To date, insulin therapy is considered the gold standard for the treatment of type 1 diabetes." (PMID 27704164, 2017). "Children with type 1 diabetes (T1D) demonstrate considerable clinical variation at diagnosis despite the vast majority having lost most of their beta-cell function (60–80% of beta-cells stop producing insulin)." (PMID 29295580, 2017).
type 1 diabetes (continued). "We have shown that autoimmunity to insulin in type 1 diabetes may result from neoepitopes induced by oxidative post-translational modifications (oxPTM)." (PMID 28526919, 2017). "Differences regarding insulin sensitivity compared with our study might be related to lower level of exertion, a longer duration of the exercise or that patients with type 1 diabetes have a different reaction pattern than the healthy participants of our trial." (PMID 28622349, 2017). "After realising HLA match through transduction of in vivo-differentiated hESC-ECs, the insulin-expressing cells could be selectively eliminated by autoreactive CTLs previously isolated from a donor with type 1 diabetes." (PMID 27787618, 2017). "The mechanism of metformin-associated ketogenesis seems to differ from lack of insulin in type 1 diabetes." (PMID 28865058, 2017). "On the other hand, one quantitative study with 18F-FDG under hyperinsulinemic-euglycemic clamping demonstrated that young male patients with less than a five-year history of insulin-dependent diabetes had similar insulin-stimulated myocardial glucose uptake compared with healthy controls." (PMID 29152121, 2017). "Thereafter, intensive insulin therapy became the standard of care in type 1 diabetes." (PMID 28620331, 2017). "The production of an insulin-secreting β-cell line, which is either resistant to recurrent autoimmunity, or able to modulate the immune system to induce tolerance, is required to reverse insulin-dependent diabetes." (PMID 27070593, 2016). "Type 1 diabetes (T1D), which affects the insulin-producing beta cells of the pancreas, and Addison’s disease (AD), which results from the destruction of the adrenal cortex, are life-threatening autoimmune conditions, leading to the absolute dependence on exogenous hormones supply." (PMID 26318769, 2016). "The effects of varying insulin pump adjustments in type 1 diabetes have been previously reported, but uncertainty still exists because of the heterogeneity of experimental conditions and exercise modality used, and reproducibility outside of controlled study environments." (PMID 27287376, 2016). "As in humans, insulin treatment can quickly reverse phenotypes and abnormalities in type 1 diabetic animals, such as diastolic dysfunction, decreased expression of sarcoendoplasmic reticulum Ca2+-ATPase 2a (SERCA2a), mitochondrial dysfunction, or oxidative stress." (PMID 27999359, 2016). "In people with type 1 diabetes, the levels of the blood sugar have not been properly controlled due to the deficient insulin production." (PMID 27535125, 2016). "Transcriptomic meta-analysis and network analysis of blood microarrays from untreated patients with PD and depression identified genes enriched in pathways related to the immune system, metabolism of lipids, glucose, fatty acids, nicotinamide, lysosome, insulin signaling and type 1 diabetes." (PMID 27680512, 2016). "We observed that serum LPS activity is associated with visceral fat mass in type 1 diabetes, independent of the traditional risk factors such as age, insulin sensitivity, and inflammation." (PMID 27958332, 2016). "Despite the life-saving nature of insulin in type 1 diabetes, poor access to insulin, accessories (i.e., needles, syringes, and test strips), and therapeutic education continue to cause unnecessary morbidity and premature mortality in developing country populations." (PMID 27379925, 2016). "These two proteins are widely used in isophane neutral protamine hagedorn (isophane NPH) formulation, which is the stoichiometric mixture of insulin and protamine at neutral pH, to subcutaneous injection, frequently utilized for basal insulin support in diabetes type 1 and type 2." (PMID 26983499, 2016).